PVRIG (PVR related immunoglobulin domain containing)
Description:
Cell surface receptor for NECTIN2. May act as a coinhibitory receptor that suppresses T-cell receptor-mediated signals. Following interaction with NECTIN2, inhibits T-cell proliferation. Competes with CD226 for NECTIN2-binding.
Synonyms: CD112R; C7orf15; MGC2463
Tractability: Antibody: UniProt places it where antibodies can reach, with high confidence; its Gene Ontology location is reachable by antibodies, with high confidence; UniProt predicts a signal peptide or a membrane-spanning region.
Gene: Protein-coding gene on chromosome 7 (100,218,241 to 100,221,490, forward strand). Ensembl gene ENSG00000213413.
Subcellular location: Cell membrane
Gene Ontology:
Molecular function: phosphatase binding; protein binding; signaling receptor activity
Biological process: negative regulation of T cell receptor signaling pathway
Cellular component: plasma membrane
Genetic constraint (gnomAD): Loss-of-function variants: 18 observed, 21.28 expected, observed/expected ratio (o/e) 0.85, 90% interval 0.58 to 1.25. The upper end of that interval is the gene's LOEUF score, 1.25, which puts it in group 5 of 6, group 1 being the genes least tolerant of losing a copy. Missense variants: 435 observed, 414.05 expected, observed/expected ratio (o/e) 1.05, 90% interval 0.97 to 1.14. Synonymous variants: 190 observed, 165.6 expected, observed/expected ratio (o/e) 1.15, 90% interval 1.02 to 1.29.
Homologues: Orthologues: chimpanzee PVRIG (98% identical), dog PVRIG (64% identical), pig PVRIG (62% identical), macaque PVRIG (58% identical), guinea pig PVRIG (55% identical), mouse Pvrig (41% identical), rat Pvrig (41% identical).
Diseases named in the same sentence as PVRIG in open-access papers:
PVRIG is named in the same sentence as 25 diseases in open-access papers, as found by Europe PMC text mining. Sharing a sentence is not in itself a finding about the gene and the disease. The quoted sentences say what the papers report.
breast carcinoma (9 papers, 2017 to 2025). "In vitro analysis showed that blockade of PVRIG or TIGIT increased the number of IFN-γ-producing NK cells under co-culture of breast cancer cells, and the combination of anti-PVRIG and anti-TIGIT antibodies induced a further increase in IFN-γ-producing NK cells and improved cytotoxicity of NK cells." (PMID 39156900, 2024). "Based on these evidences, PVRIG can be considered a therapeutic target and its blockade in vivo could imply a novel approach to improve trastuzumab efficacy in human breast cancer." (PMID 31234588, 2019). "In line with our data positive (co-) expression of TIGIT and PVRIG or CD39 was recently detected on CD8+ T cells derived from the primary site of several tumor types including lung, breast cancers and acute leukemia." (PMID 40274631, 2025). "In humans, blockade of PVRIG and TIGIT has been shown to enhance trastuzumab-mediated NK cell response against breast cancer." (PMID 31234588, 2019).
colon cancer (2 papers, 2021). "In MC38 colon cancer model, PVRIG-deficient mice showed significantly slower tumor growth (P < 0.0001) and longer survival time (P < 0.001) compared with wild-type mice." (PMID 34174928, 2021). "Mice were subcutaneously inoculated with MC38 tumor cells to generate murine colon tumor models, followed by treatment with anti-PVRIG mAb, rat IgG, or PBS on day 3 post-tumor graft (tumor size was around 10 mm3)." (PMID 34174928, 2021). "However, the percentage of PVRIG+ NK cells among TILs was significantly higher in three murine models of subcutaneously administered tumors (MC38 colon cancer, MCA205 fibrosarcoma and LLC lung cancer) compared with those in the spleen of normal mice and tumor-bearing mice (P < 0.0001)." (PMID 34174928, 2021). "To illustrate the effect of PVRIG on NK cells in tumor microenvironment, we compared PVRIG+ and PVRIG− tumor-infiltrating NK cells from three murine tumor models (MC38 colon cancer, MCA205 fibrosarcoma and LLC lung cancer)." (PMID 34174928, 2021). "It was reported previously that treatment with anti-PVRIG mAb alone shows no inhibitory effect on tumor growth in murine CT26 colon cancer model, consistent with their study, we observed no influence of anti-PVRIG mAb on CT26 tumor-bearing mice (data not shown)." (PMID 34174928, 2021).
acute GVHD (1 paper, 2024). "We found weak genetic associations between polymorphisms in the CD226, CD244, FCGR3A, KLRD1, NCR3, and PVRIG genes, and the risks for relapse, acute GVHD, and chronic GVHD in the HSCT discovery cohort but not in the replication cohort." (PMID 39506082, 2024).
colorectal cancer (1 paper, 2024). A primary or metastatic malignant neoplasm that affects the colon or rectum. "In PVRIG-deficient mouse models of melanoma and colorectal cancer, tumor growth is suppressed, and tumor-infiltrating CD8+ T cells are increased." (PMID 39156900, 2024). "In a colorectal cancer model, PD-L1 blockade inhibited tumor growth in PVRIG-deficient mice but not in wild-type mice." (PMID 39156900, 2024).
glioma (1 paper, 2022). A benign or malignant brain and spinal cord tumor that arises from glial cells (astrocytes, oligodendrocytes, ependymal cells). "Immune checkpoint blockade was an important strategy for glioma treatment; several regular checkpoint molecules were included in our study, and it indicated that except for PVRIG, CD200, and VTCN1, immune checkpoints were substantially higher in the high-risk group." (PMID 36281290, 2022).
leukemia (1 paper, 2019). A malignant (clonal) hematologic disorder, involving hematopoietic stem cells and characterized by the presence of primitive or atypical myeloid or lymphoid cells in the bone marrow and the blood. "Analysis of DNAM-1, TIGIT, TACTILE and PVRIG on human NK cells from solid cancer or leukemia patients will clarify the role of these receptors in cancer surveillance." (PMID 31234588, 2019). "In NK cells from patients with solid cancer and leukemia, it has been observed a decreased expression of DNAM-1 that may shift the balance in favor to the inhibitory receptors TIGIT or PVRIG, further contributing to the diminished NK cell-mediated cytotoxic capacity observed in these patients." (PMID 31234588, 2019).
myelogenous leukemia (1 paper, 2024). "A coculture system of purified NK cells with the myelogenous leukemia cell line K562, which expresses high levels of PVRL2, was used for the study of PVRIG mAb-mediated NK function." (PMID 38554184, 2024).
tumor (34 papers, 2017 to 2026). "Higher percentage of CD107a+, GzmB+ and IFN-γ+ tumor-infiltrating NK cells were observed respectively in PVRIG-deficient mice." (PMID 34174928, 2021). "Next, we subcutaneously administered tumor cells (MC38, MCA205 and LLC) to normal mice and PVRIG-deficient mice to investigate the effect of PVRIG on tumor growth and the survival of tumor-bearing mice." (PMID 34174928, 2021). "PVRIG High tumors were characterized by a higher lymphocytic infiltrate and enriched for signatures associated with tertiary lymphoid structures and better anti-tumor immune response." (PMID 36672396, 2023). "Furthermore, the proliferation of tumor-infiltrating NK cells was enhanced in PVRIG-deficient mice as indicated by the Ki67 expression (P < 0.001)." (PMID 34174928, 2021). "Furthermore, PVRIG-deficient mice display significantly reduced tumor growth due to enhanced CD8+ T cell function." (PMID 34174928, 2021). "To evaluate the importance of PVRIG during tumor progression, we generated PVRIG-deficient mice." (PMID 34174928, 2021). "Furthermore, either PVRIG deficiency, early blockade or late blockade of PVRIG slowed tumor growth and prolonged survival of tumor-bearing mice by inhibiting exhaustion of NK cells as well as CD8+ T cells." (PMID 34174928, 2021). "Further, by using PVRIG-deficient mice and self-generated anti-mouse PVRIG mAb, we showed that PVRIG deficiency or PVRIG blockade (both early and late treatments) could reduce the tumor size and prolong the survival of tumor-bearing mice through inhibiting NK cell and CD8+ T cell exhaustion." (PMID 34174928, 2021). "Poliovirus receptor-related protein 2 (PVRL2), also known as CD112, expressed by tumor cells and tumor-associated myeloid cells, binds the late-induced inhibitory receptor PVRIG (CD112R) on activated CD8+ T cells." (PMID 41268548, 2025). "In line with our data, high expression of TIGIT and PVRIG on cytotoxic NK cells has been recently described as sign of exhaustion in NK cells infiltrating primary tumor sites." (PMID 40274631, 2025). "As previously reported, PVRIG is more highly expressed in the tumor microenvironment than in the periphery, and abundant FcγR-expressing myeloid cells infiltrate tumors, creating a highly immunosuppressive environment." (PMID 38554184, 2024). "Tumor-bearing mice treated with the anti-PVRIG mAb presented a significantly greater number of NK cells (NKp46+ in CD45+ cells) and upregulation of CD107a, while the number of total CD8+ T cells remained unchanged after the first dose." (PMID 38554184, 2024). "PVRL2 and PVR are predominantly expressed on tumor cells and antigen-presenting cells, binding to PVRIG and TIGIT, respectively, which are primarily found on T and NK cells, thereby suppressing antitumor immunity." (PMID 39156900, 2024). "Although the anti-PVRIG mAb significantly inhibited tumor growth, NK cell depletion abolished this effect in tumor-bearing mice." (PMID 38554184, 2024). "This phenomenon has also been observed in PVRIG knockout mice, in which tumor-infiltrated T cells exhibit enhanced IFN-γ and TNF-α production." (PMID 38554184, 2024). "PVRIG inhibition effectively suppresses tumor growth and prolongs the survival of tumor-bearing mice, which is associated with enhanced frequency and cytotoxicity of tumor-infiltrating NK cells." (PMID 39156900, 2024). "In summary, our study demonstrated the antitumor effect and tumor immune activation of the anti-PVRIG mAb IBI352g4a in preclinical studies." (PMID 38554184, 2024). "PVR+PVRL2+ tumor cells are the most abundant compared to other cancers and have higher PVRIG expression." (PMID 39156900, 2024). "Overall, these trials suggest that blocking the PVRIG/NECTIN-2 interaction to enhance anti-tumor cytotoxic function is a new therapeutic opportunity for the treatment of solid tumors." (PMID 36672396, 2023).
tumor (continued). "In this setting, analysis of pre-treated tumor samples will allow to assess PVRIG expression and to test if it can predict the therapeutic response." (PMID 36672396, 2023). "In murine models with solid tumors, PVRIG interaction with its ligand NECTIN-2 on tumor or dendritic cells surface suppresses cytotoxic signals, cytokines production, and triggers exhaustion." (PMID 36672396, 2023). "Recent results suggest that PVRIG expression is reduced during human NK-cell activation, while exhausted tumor-infiltrating NK cells express high levels of PVRIG." (PMID 35164813, 2022). "It was reported that nectin-2 binds to PVRIG on NK and T cells, thereby limiting their anti-tumor activity." (PMID 36293219, 2022). "An example for these paired receptors pose the Ig superfamily receptors DNAM-1, TIGIT, CD112R/PVRIG and CD96/TACTILE which bind to tumor associated ligands of the Nectin or Nectin-like (Necl) family." (PMID 35371071, 2022). "Our study showed higher expression of Ki67, CD107a, GzmB and IFN-γ in the tumor-infiltrating CD8+ T cells from PVRIG-deficient mice, suggesting that besides NK cells, CD8+ T cells in PVRIG-deficient mice were also more functional." (PMID 34174928, 2021). "In COAD and READ, the expression of PVR/CD155, PVRL1/CD111, PVRL2/CD112, TIGIT, and PVRIG/CD112R was significantly higher in tumor tissues than that in normal tissues." (PMID 33581644, 2021). "Genetic knock-out of PVRIG in mice or treatment with anti-PVRIG mAb (both early and late treatments) significantly inhibited the exhaustion of NK cells and slowed tumor growth in several murine tumor models." (PMID 34174928, 2021). "Tumor-bearing mice treated with anti-PVRIG mAb showed lower expression of inhibitory receptors CD96 and PD-1 and higher expression of activating receptor NKG2D and cytotoxic molecule TRAIL on tumor-infiltrating NK cells." (PMID 34174928, 2021). "The results indicated that early treatment with anti-PVRIG mAb significantly inhibited tumor growth (P < 0.0001) and extended the overall survival (P < 0.0001) of tumor-bearing mice compared with the control groups." (PMID 34174928, 2021). "In summary, our study, for the first time to our knowledge, illustrated that tumor-infiltrating PVRIG+ NK cells were exhausted in tumor microenvironment." (PMID 34174928, 2021). "Smaller tumor size and lower tumor weight (P < 0.001) were also observed on day 28 after tumor challenge in mice treated with anti-PVRIG mAb." (PMID 34174928, 2021). "The results showed that the use of anti-PVRIG mAb significantly inhibited tumor growth in Rag1−/− mice compared to those treated with control antibody (P < 0.001), suggesting that anti-PVRIG mAb was effective even in the absence of adaptive immunity." (PMID 34174928, 2021). "The results indicated that late treatment with anti-PVRIG mAb significantly inhibited tumor growth (P < 0.0001) and prolonged the overall survival of tumor-bearing mice (P < 0.01)." (PMID 34174928, 2021). "Consistent with our previous results (here as positive control), anti-PVRIG mAb significantly inhibited tumor growth (P < 0.0001) and prolonged overall survival (P < 0.0001) of tumor-bearing mice." (PMID 34174928, 2021). "The blockade of PVRIG using this mAb enhanced the cytokine secretion and cytotoxicity of human NK cells against various tumor cell lines in vitro." (PMID 34174928, 2021). "In a similar way the recognition of CD112 on tumor cells by PVRIG expressed on T and NK cell is considered as a novel checkpoint." (PMID 31234588, 2019). "The DNAM-1 activating receptor and the TIGIT/PVRIG/TACTILE inhibitory axis have been shown to be key regulators of anti-tumor immune responses." (PMID 31234588, 2019). "Moreover, first functional evaluation proofed that blockade of TIGIT and/or PVRIG prevented NK cell exhaustion and promotes NK cell–dependent tumor immunity in solid and hematological tumor models." (PMID 40274631, 2025).
tumor (continued). "Furthermore, anti-PVRIG antibodies have been reported to inhibit tumor progression alone or in combination with PD-L1 inhibitors." (PMID 39156900, 2024). "Collectively, these results demonstrated that blocking PVRIG elicited potent NK cell activation first, followed by T-cell activation, resulting in potent systemic antitumor immunity against tumors and tumor growth delay via both cytotoxic TIL activation and exhaustion prevention." (PMID 38554184, 2024). "However, the efficacy of anti-PVRIG was abolished in mice tumor models when either T or NK cells have been depleted." (PMID 38554184, 2024). "However, inhibiting PVRIG using anti-PVRIG blockade significantly enhanced T-cell and NK cell cytotoxicity against several tumor cells in vitro." (PMID 38554184, 2024). "Additionally, we identified activated intermediate monocytes with upregulation of the gene expressing the inhibitory receptor PVRIG, which has been shown to regulate NK cell-mediated anti-tumor activity." (PMID 37874153, 2023). "Taken together, these data suggest that PVRIG is a tumor suppressor gene in cancer." (PMID 37542274, 2023). "In these tumors, precluding the PVRIG/NECTIN-2 interaction might unleash a cytotoxic anti-tumor immune response and improve the clinical outcome." (PMID 36672396, 2023). "Notably, tumor-infiltrating CD8+ T cells and NK cells from PVRIG-deficient mice exhibit increased proinflammatory cytokine production, suggesting that PVRIG is involved in direct or indirect modulation of tumor-infiltrating T/NK cells." (PMID 35812451, 2022). "Besides, IFN-γ secretion was significantly improved in tumor-bearing mice treated with anti-PVRIG mAb compared with those treated with rat IgG." (PMID 34174928, 2021). "Indeed, our study showed that combined blockade of PVRIG and PD-L1 significantly reduced tumor size in MC38 tumor-bearing mice and resulted in better therapeutic effects than using either mAb alone." (PMID 34174928, 2021). "Furthermore, use of anti-PVRIG mAb also enhanced the cytotoxic potential of tumor-infiltrating NK cells, indicated by higher expression of CD107a and GzmB." (PMID 34174928, 2021). "The upregulation of PVRL2 in tumor tissues may be the main reason for the over-expressed PVRIG observed in TILs." (PMID 34174928, 2021). "Consistent with their study, we showed that both genetic deficiency and blockade of PVRIG could enhance the cytotoxicity and IFN-γ production of tumor-infiltrating CD8+ T cells in MC38 tumor-bearing mice." (PMID 34174928, 2021). "Furthermore, we generated mouse anti-human PVRIG mAb and found that anti-human PVRIG (anti-hPVRIG) slowed tumor growth in both human NK cell- and peripheral blood mononuclear cell (PBMC)-reconstituted xenograft murine models." (PMID 34174928, 2021). "Therefore, in addition to the early treatment, we also treated mice with anti-PVRIG mAb when MC38 tumor size reaches 100–150 mm3." (PMID 34174928, 2021). "We found that PVRIG was highly expressed on tumor-infiltrating NK cells with exhausted phenotype." (PMID 34174928, 2021). "As expected, blocking human PVRIG significantly reduced the tumor size in NK cell-reconstituted xenograft mice, suggesting that PVRIG blockade could be effective by acting only on NK cells." (PMID 34174928, 2021). "PVRIG is a recently identified immune checkpoint receptor and blockade of which could reverse T cell exhaustion to treat murine tumor; however, its therapeutic potential via NK cells in mice and human remains seldom reported." (PMID 34174928, 2021). "PVRIG was reported to be involved in the exhaustion of CD8+ T cells during tumor progression." (PMID 34174928, 2021). "Collectively, these results demonstrated that therapeutically blocking PVRIG in vivo elicited potent systemic anti-tumor immunity against established tumors and inhibited tumor growth possibly by reversing the exhaustion of tumor-infiltrating NK cells as well as CTLs." (PMID 34174928, 2021).